MYC (MYC proto-oncogene, bHLH transcription factor)
Diseases named in the same sentence as MYC in open-access papers (continued):
Sharing a sentence is not in itself a finding about the gene and the disease.
prostate carcinoma (continued). "To demonstrate the utility of dPCR in quantifying chromatin interactions, we examined two prostate cancer risk loci at 8q24 and 2p11.2 for their interaction target genes MYC and CAPG in LNCaP cell line." (PMID 27923366, 2016). "For example, we observed strong interactions of MYC gene region with prostate cancer risk region 1 (E128-129) in the LNCaP cancer cell line but not in LCLs." (PMID 26979803, 2016). "We tested this assay at two prostate cancer risk regions of 8q24 and 2p11.2 for their interaction target genes MYC and CAPG." (PMID 27923366, 2016). "The next question was to determine the signaling pathway(s) that underlay the regulation of c-MYC stability by SIRT3 in prostate cancers." (PMID 26317998, 2015). "A negative correlation has been found between the aggressiveness of prostate cancer (Gleason score and pathological state) and the global loss of H3K27me3 which is linked to MYC over-expression." (PMID 24398858, 2014). "Amplification of the MYC locus is frequent in prostate cancer (30%) and is associated with disease progression and Gleason score." (PMID 24293458, 2013). "The most extensively studied genetic variant in the 8q24 gene desert upstream of MYC gene is the colorectal and prostate cancer risk SNP rs6983267." (PMID 23752272, 2013). "Recent studies have demonstrated strong association between MYC overexpression in prostate cancer tissues and clinical progression." (PMID 22191037, 2011). "We identified an association between PI3K-pathway alteration and MYC amplification in a cohort of primary and metastatic human prostate cancer samples." (PMID 21394210, 2011). "One study used PC3 human prostate carcinoma cells to show that Pim1 overexpression accelerates tumorigenicity in these cells associated with elevated levels of c-MYC and the phosphorylation of proteins involved in protein synthesis." (PMID 20515470, 2010). "The colorectal and prostate cancer SNP rs6983267 has been shown to affect TCF4 binding to an enhancer for MYC, providing a mechanistic basis for an 8q24.21 association." (PMID 21307401, 2010). "c-MYC overexpression is a common early event in prostate cancer while PTEN is deleted/mutated in ∼30% of primary human prostate cancers." (PMID 19578399, 2009). "Quantitative analysis of c-MYC expression in normal prostate tissues suggests an association between overexpression and variants in Region 1 of prostate cancer risk." (PMID 18190704, 2008). "Overall, the scan analysis suggests the existence of 8q24 cis-regulators of germline c-MYC transcription in lymphocytes, partially overlapping with Region 1 of prostate cancer risk." (PMID 18190704, 2008). "The scan revealed a possible association between variants in Region 1 of prostate cancer risk and differential germline expression of c-MYC." (PMID 18190704, 2008). "Transcriptional targets of MYC include many genes that were identified as conferring risk of prostate cancer and/or being somatically mutated in prostate tumors." (PMID 18190704, 2008). "Although larger sample series are required to draw definitive conclusions, the quantitative analysis of geneexpression in normal prostate tissues supports the model of c-MYC overexpression associated with Region 1 of prostate cancer risk." (PMID 18190704, 2008). "This study proposes that variation at putative 8q24 cis-regulator(s) of transcription can significantly alter germline c-MYC expression levels and, thus, contribute to prostate cancer susceptibility by down-regulating the prostate tumor suppressor KLF6 gene." (PMID 18190704, 2008). "From the perspective of signaling pathways, mainstream research indicates that glutamine addiction is associated with the progression and metastasis of prostate cancer cells through three distinct pathways: the AR pathway, the MYC pathway, and the PTEN/PI3K/mTOR pathway." (PMID 41179661, 2025).
prostate carcinoma (continued). "For example, MYC encodes the transcription factor MYC, which is the third most amplified gene in human cancers and is overexpressed in several cancer subtypes, including prostate cancer." (PMID 39272896, 2024). "Because we and others have linked MYC overexpression to prostate cancer development and progression, and because MYC has been shown to induce mitochondrial biogenesis, we also investigated the role of MYC in regulating mtDNAcn in human and murine prostate cancer cells." (PMID 37971875, 2023). "High levels of MYC were linked to aggressive prostate cancer and triple-negative breast cancer." (PMID 37193964, 2023). "Similarly to the MYC-driven genetically engineered prostate cancer mouse model, MYC overexpression in LNCaP cells was associated with the depletion of the Hallmark Androgen_response gene set." (PMID 35562350, 2022). "PssGSEA indicated that the MYC Targets VI hallmark was increased in clusters 5, 6, and 11, suggesting that this alteration may be common among several Gleason patterns of prostate cancer." (PMID 36229464, 2022). "Chromatin conformation capture and dCas9-mediated enhancer blocking studies place the high-risk variant within a prostate cancer–specific enhancer region, serving to modulate expression of MYC, PCAT1, PRNCR1, and other 8q24 genes implicated in prostatic carcinogenesis." (PMID 35104804, 2022). "Importantly, about 25% of familial risk of prostate cancer map to germline variation at chromosome 8q24 with mechanistic evidence tying this region to MYC regulation." (PMID 35562350, 2022). "Importantly, our analyses exposed a subtype of primary prostate cancer characterized by divergent AR (low) and MYC (high) transcriptional signatures that are predisposed to fail standard-of-care therapies and progress to the mCRPC stage." (PMID 35562350, 2022). "Moreover, we found that dilazep suppressed, in all three lines, a recently described MYC/RAS co-activation signature (META-16) that is associated with prostate cancer metastasis." (PMID 34636746, 2021). "Moreover, the TMPRSS2-ERG fusion event is associated with overexpression of the oncogene MYC in prostate cancer cells, which further contributes to promote cell growth and proliferation." (PMID 34638309, 2021). "Thus, Priolo and coworkers have shown that prostate cancer associated with predominant MYC overexpression display dysregulated lipid metabolism, while tumors with predominant AKT1 activation were associated with accumulation of aerobic glycolysis metabolites." (PMID 31366128, 2019). "Accordingly, the prostate cancer susceptibility locus at Xp11.2 could be related to the regulation of the MYC oncogene expression level." (PMID 30863497, 2019). "Interestingly, at the bq24 locus maps several prostate cancer susceptibility genes; however, despite the close proximity to the MYC locus, no direct association was found between 8q24 risk alleles and MYC expression in normal and tumor human prostate tissues." (PMID 31366128, 2019). "Inactivation and/or mutations of TSPX and/or FOXP3 tumor suppressors at the Xp11.2 locus might impair their regulatory functions on MYC expression, thereby exacerbating the susceptibility of prostate cancer initiation and progression." (PMID 30863497, 2019). "Trock and coworkers performed an analysis of some common genetic alterations of prostate cancer (chromosome 8q gain (MYC), 8p loss, and PTEN loss) in adjacent GP3 and GP4 tumors in GS6 and GS7 tumors: 8q gain, 8p loss and PTEN loss were more common in G3 cores derived from GS7 than GS6 tumors." (PMID 31366128, 2019). "4C-seq with GWAS was used to identify a risk locus for prostate cancers (LNCaP and C4-2B cells), and MYC and POU5F1B were ranked the highest, followed by CD96, PVT1, GSDMC, CXorf36, RRP12, USP14 and SMIN3, which may exhibit abnormal chromatin looping." (PMID 29149895, 2017).
prostate carcinoma (continued). "In line with this hypothesis, the 8q24 localized and prostate cancer associated SNP (rs6983267) was shown to increase MYC expression only during prostate development/maturation before the onset of tumorigenesis." (PMID 27282637, 2016). "Indeed, the increasing levels of MYC in castration-resistant prostate cancer result in a global loss of H3K27me3 and hence a global decrease in DNA methylation which is a characteristic feature of late- or end-stage metastatic prostate cancer." (PMID 24398858, 2014). "The MYC gene is located in the 8q24 region, in which several susceptibility loci were identified by GWAS for many epithelial cancers including colorectal cancer, prostate cancer, breast cancer and bladder cancer." (PMID 23752272, 2013). "Interestingly, we found c-MYC level and activity is directly regulated by PTEN expression and a significant overlap between hi-c-Myc and Pten null or mAKT1 prostate cancer models in their associated prostate cancer-associated TFAs." (PMID 22347425, 2012). "For example, the colorectal and prostate cancer predisposition locus contains an enhancer that is able to interact with the MYC gene and it was suggested that rs6983267 within this enhancer alters a TCF7L2 (TCF4) binding site thus resulting in changed sensitivity to WNT signalling." (PMID 21814516, 2011). "Our study further proposes that germline c-MYC overexpression may promote cellular transformation of the normal epithelium and, by extension, risk of prostate cancer by down-regulating the prostate tumor suppressor KLF6 gene." (PMID 18190704, 2008). "Furthermore, PIM1 has been observed to enhance MYC‐induced tumorigenicity in human PCa in a mouse xenograft model, while coexpression of PIM1 and MYC in human PCa is associated with higher Gleason scores, suggesting that these oncoproteins synergize to induce advanced prostate carcinoma." (PMID 33932111, 2021). "There is growing evidence for a role of epigenetic mechanisms at chromosome 8q24 in prostate cancer based on the identification of gene regulatory elements at this locus, as well as long-range tissue-specific interactions between 8q24 cancer susceptibility loci and MYC." (PMID 33374332, 2020). "In the present study, our primary aim was to investigate whether MYC exon 3 DNA methylation in prostate tumor tissue was associated with tumor aggressiveness based on Gleason score (GS), an intermediate prognostic marker for prostate cancer." (PMID 33374332, 2020). "As another secondary aim, we investigated whether the association between MYC DNA methylation and GS varied by race (African American vs. Caucasian) given striking disparities in prostate cancer outcomes by race and growing evidence for a role of biological differences in tumor." (PMID 33374332, 2020). "The Hi-Myc mouse model expresses human c-MYC in the prostate and recapitulates human prostate cancer on a genetic level, since cancers harbor loss of the tumor suppressor Nkx3.1 and upregulation of the serine/threonine kinase Pim-1, which are also prevalent in human prostate cancer." (PMID 29212195, 2017). "Therefore, we suggest that differential binding of YY1 to the prostate-cancer associated variant rs378854 might be functionally important for the regulation of MYC and/or PVT1 expression." (PMID 21814516, 2011). "We sought to identify which of these genes, particularly those conferring risk of prostate cancer, could be functionally associated with c-MYC by examining the similarity between expression profiles using a data set containing 50 normal tissues and 52 prostate tumors." (PMID 18190704, 2008).
prostate carcinoma (continued). "The rs10808558 A allele showed an association with c-MYC overexpression in YRIs (expression difference of 0.23 log2 units, 95% confidence interval (CI) 0.06 – 0.41; P = 0.007) and this SNP is in low linkage disequilibrium (LD) with the prostate cancer risk variant rs1447295 (r2 = 0.19)." (PMID 18190704, 2008). "This expands previous studies reporting on the control of EIF4EBP1 transcription by MYC in colorectal and prostate cancer cells." (PMID 40670359, 2025). "We cultured c-Myc driven murine prostate cancer cells (MyC-CaP) and treated them with 0.5 μM rucaparib (Ruc), a clinically used PARP inhibitor." (PMID 41332572, 2025). "In this study, we identified ABHD5 as a novel suppressor of c-MYC-driven transcriptional programs in prostate cancer cells through unbiased transcriptomic profiling." (PMID 41349769, 2025). "A recent article reported that USP11 can deubiquitinate and stabilize the MYC and AR proteins, thereby promoting prostate cancer progression." (PMID 39990228, 2025). "SH-BC-893 also reduced nuclear YAP levels in MYC-CaP, LNCaP, and 22Rv1 prostate cancer cells demonstrating that the effect is not restricted to mPCE cells." (PMID 40588551, 2025). "Intriguingly, our previous work has demonstrated that menin interacts with β-catenin and controls the binding of β-catenin to the MYC promoter in prostate cancer cells." (PMID 40837414, 2025). "It promotes aggressive behavior in NSCLC and prostate cancer via activation of ERK/MYC and STAT3 signaling, respectively, while in medullary thyroid carcinoma, it correlates with nodal spread through YAP1 suppression." (PMID 40940980, 2025). "MYC functions as a central regulator of glutamine metabolism in prostate cancer by repressing miR-23a/b, thereby relieving the inhibition of mitochondrial GLS and promoting glutaminolysis, particularly in androgen-independent PC-3 cells." (PMID 41179661, 2025). "To determine the functional significance of ABHD5-mediated c-MYC suppression in prostate cancer cell growth, we examined the proliferative capacity of ABHD5-deficient 22Rv1 cells." (PMID 41349769, 2025). "Glutamine metabolism in prostate cancer is also regulated by oncogenes like MYC, androgen receptors (AR), and mTOR, with metabolic tracing studies highlighting glutamine’s role in energy and precursor synthesis." (PMID 41179661, 2025). "In this review, we focus on the roles of transcriptional CDKs in prostate cancer growth, metastasis and therapy resistance and discuss their interplay with AR, MYC and BRD4." (PMID 40163908, 2025). "Consistent with the known upregulation of MYC in human prostate cancer, the IHC staining quantification showed robust MYC expression which correlated with CRIPTO expression (**p = 0.0098)." (PMID 39592836, 2025). "Regarding prostate carcinoma, miR-32 was demonstrated to facilitate tumor development and proliferation in MYC-driven environments." (PMID 40711670, 2025). "The development of MRT‐2359 for MYC‐driven NSCLC was converted to the development of prostate cancer due to the inability to determine MYC expression levels of patients, while the HER2‐DAC ORM‐5029 pipeline was also discontinued." (PMID 41194439, 2025). "This phenomenon was first observed in PC3, a prostate cancer cell line model known to have extrachromosomal MYC amplification." (PMID 40787829, 2025). "Here, we identify ABHD5 as a suppressor of c-MYC-driven transcriptional programs in prostate cancer cells." (PMID 41349769, 2025). "For example, CDK7 is an important regulator of both factors, at least in part because it phosphorylates MED1 to enhance AR- and MYC-regulated transcription in prostate cancer." (PMID 40163908, 2025). "In short, there remains much to understand about the context-dependent relationship between MYC and AR; given the central role of these factors in prostate cancer, further research in this area is certainly warranted." (PMID 40163908, 2025).
prostate carcinoma (continued). "Studies on the role of LSD1 in prostate cancer have demonstrated that LSD1 inhibitors suppress MYC signaling and reduce tumor growth." (PMID 40428124, 2025). "In prostate cancer, elevated c-MYC expression is frequently observed and strongly correlates with disease aggressiveness, therapy resistance, and poor clinical outcomes." (PMID 41349769, 2025). "Research indicates that in the context of MYC-driven prostate cancer, miR-32 significantly facilitates tumor development and proliferation." (PMID 40711670, 2025). "This was particularly intriguing as it was associated with PSA progression, further suggesting a potential synergistic role between CRIPTO, MYC targets, and the advancement of prostate cancer-promoting tumorigenesis." (PMID 39592836, 2025). "This study identifies ABHD5 as a novel suppressor of c-MYC-driven oncogenic signaling in prostate cancer, revealing a previously unrecognized, lipase-independent mechanism underlying its tumor-suppressive activity." (PMID 41349769, 2025). "To address this unmet need, we conducted a genome-wide CRISPR knockout (KO) screen in two biological replicates using murine MycCaP prostate cancer cells and the well-characterized small-molecule MYC inhibitor MYCi975." (PMID 40668928, 2025). "Integrative omics analyses reveal that MYC orchestrates ammonium metabolism reprogramming in prostate cancer through direct transcriptional control of GLS, with TCGA-PRAD data confirming co-amplification of MYC and GLS (q < 0.001)." (PMID 41179661, 2025). "The results demonstrated that NCAPD3 promoted tumor growth in prostate cancer through down-regulating miR-30a-5p, which was associated with the regulation of STAT3, MYC, and EZH2." (PMID 38561330, 2024). "It is believed that genetic aberrations at this location can result in influenced expression within the MYC gene, resulting in prostate cancer development." (PMID 39410867, 2024). "In the same manner, we investigated the generalizability of the technology in targeting c-MYC across other cancer types such as medulloblastoma and prostate cancer." (PMID 39123391, 2024). "Our findings provide evidence that KLF6-SV1 is an enhancer of c-MYC-driven prostate cancer progression and metastasis, and a correlated genetic event in human prostate cancer with potential translational significance." (PMID 38352401, 2024). "Transgenic mice that co-expressed KLF6-SV1 and c-MYC developed progressive and metastatic prostate cancer with a histological and molecular phenotype like human prostate cancer." (PMID 38352401, 2024). "Our study identified a high frequency of CNAs in MYC in breast, ovary, and prostate cancer patients, shedding light on its potential role across multiple cancer types." (PMID 38674331, 2024). "High MYC expression is associated with increased levels of SRPK1 in patient samples, and overexpression of MYC sensitizes prostate cancer cells to SRPK1 inhibition using pharmacological and genetic strategies." (PMID 38775167, 2024). "CRPC-specific AR binding regions are not primarily occupied by typical AR-cooperating factors observed in hormone-sensitive prostate cancer cells but rather by AR-independent transcription factors, such as MYC." (PMID 38698344, 2024). "Here, we evaluate CDKI-73’s activity in prostate cancer and demonstrate that it promotes apoptosis and inhibits signaling by AR, MYC, and BRD4." (PMID 39117800, 2024). "We performed a dose–response study using previously designed PPRHs against KRAS and MYC in the prostate cancer cell line PC-3." (PMID 39457457, 2024). "In this work we focused on our understanding of the cooperative dynamics between these oncogenes, by investigating the combined impact of PPRHs targeting KRAS and MYC in pancreatic and prostate cancer cells." (PMID 39457457, 2024).